SCN1B (sodium voltage-gated channel beta subunit 1)
Diseases named in the same sentence as SCN1B in open-access papers (continued):
Sharing a sentence is not in itself a finding about the gene and the disease.
breast carcinoma (3 papers, 2010 to 2018). "SCN1B expression is decreased in highly metastatic breast cancer cells lines, but is increased in highly metastatic prostate cancer cell lines." (PMID 29723302, 2018). "In this study, we found that SCN1B gene is downregulated in breast cancer compared with normal breast tissues." (PMID 27917859, 2016). "An initial in vitro study indicated that the expression of SCN1B/β1 was higher in poorly invasive than in highly invasive breast cancer cells." (PMID 27917859, 2016). "In breast cancer, enforced SCN1B expression could promote pathological growth and cellular dissemination, including metastasis to both lung and liver." (PMID 29723302, 2018). "In contrast, a recent study demonstrated that SCN1B/β1 was overexpressed in breast cancer biopsies, compared with non-cancer breast samples." (PMID 27917859, 2016).
Failure to thrive (3 papers, 2019 to 2025). Failure to thrive (FTT) refers to a child whose physical growth is substantially below the norm. "Thus, it is not surprising that DS patients, including those with SCN1B gene variants, present with comorbid GI symptoms, including feeding difficulties, constipation, and failure to thrive." (PMID 39847501, 2025). "Treatment of Scn1b−/− mice with bumetanide resulted in a delay in SUDEP onset compared to controls in a subset of mice, without prevention of seizure activity or amelioration of failure to thrive." (PMID 30996233, 2019).
AV block (2 papers, 2018 to 2024). "On the other hand, there are more patients in whom no cause of the AV block could be found, which is so-called idiopathic AV block (progressive cardiac conduction disease), which has been linked to a strong genetic background, i.e., gene mutations involving SCN5A and SCN1B." (PMID 29686877, 2018).
breast tumors (2 papers, 2014 to 2020). "Expression of the NaV1.5 isoform in breast tumors was found to be correlated with metastases development and patients’ death, and SCN1B mRNA was also discovered to be more abundant in highly invasive prostate cancer cell lines." (PMID 32207560, 2020). "Our data support the hypothesis that SCN1B/β1 recapitulates its neurodevelopmental role to promote breast tumour growth and metastasis." (PMID 24729314, 2014).
Early Infantile Epileptic Encephalopathy (2 papers, 2019 to 2022). "Patients with Early Infantile Epileptic Encephalopathy (EIEE) 52 have inherited, homozygous variants in the gene SCN1B, encoding the voltage‐gated sodium channel (VGSC) β1 and β1B non‐pore‐forming subunits." (PMID 31709768, 2019).
heart failure (2 papers, 2021 to 2022). Inability of the heart to pump blood at an adequate rate to meet tissue metabolic requirements. "Thus, experiments involving the imposition of risk factors on cardiac specific Scn1b-null animals, including age and female sex, are granted and may clarify the consequences of enhanced Na+ influx and diastolic impairment on the development of heart failure." (PMID 35394857, 2022).
ovarian carcinoma (2 papers, 2021 to 2023). A malignant neoplasm originating from the surface ovarian epithelium. "In the case of NaV β subunits, RNA sequencing analysis revealed Nav channel expression in 48 ovarian cancer cell lines, showing a reduced expression of SCN8A (NaV1.6) and SCN1B (sodium voltage-gated channel beta subunit 1) in cancer cells." (PMID 37375748, 2023). "We found that ovarian cancer cells generally express lower levels of voltage-gated sodium channels than normal cells and that two voltage-gated sodium channels, SCN8A and SCN1B, were prognostic biomarkers for ovarian cancer overall survival." (PMID 34771603, 2021).
temporal lobe epilepsy (2 papers, 2015 to 2022). A localization-related (focal) form of epilepsy characterized by recurrent seizures that arise from foci within the temporal lobe, most commonly from its mesial aspect. "Studies have firmly established the relationship between SCN1B, coding for accessory beta subunit, and GEFS+ as well as extending the phenotype to include temporal lobe epilepsy in some families." (PMID 25893123, 2015).
autism (1 paper, 2022). Persistent deficits in social interaction and communication and interaction as well as a markedly restricted repertoire of activity and interest as well as repetitive patterns of behavior. "We hypothesize that genes severely dysregulated in autism such as SCN1B, KCNAB3, FMN1, or VAMP1 might additionally contribute to the excitation-to-inhibition ratio affecting normal network function and circuitry." (PMID 35680911, 2022).
Bradycardia (1 paper, 2022). A slower than normal heart rate (in adults, slower than 60 beats per minute). "In a previous study comparing surface ECG recordings in anesthetized P17–18 Scn1b-null and WT mice, we reported that null mice had bradycardia, suggesting altered sinoatrial node (SAN) function, and prolonged corrected Q-T interval (QTc), suggesting altered ventricular function." (PMID 35603785, 2022). "Evaluation of ECG properties in animals at increasing postnatal developmental time points demonstrated that bradycardia and QTc prolongation become evident by P14 in the null mice, suggesting that Scn1b deletion results in developmentally regulated alterations in SAN as well as ventricular function." (PMID 35603785, 2022).
brain injury (1 paper, 2023). Acute and chronic (see also brain INJURIES, CHRONIC) injuries to the brain, including the cerebral hemispheres, CEREBELLUM, and brain STEM. "We aimed to investigate the correlation between miRNA-210 and SCN1B, a voltage-gated sodium channel gene, in brain tissue of fetal rats with hypoxic-ischemic brain injury." (PMID 36541246, 2023).
cervical cancer (1 paper, 2018). A primary or metastatic malignant neoplasm involving the cervix. "In cervical cancer tissues, SCN3B mRNA level is increased, whereas SCN1B, SCN2B and SCN4B mRNA levels are decreased." (PMID 29723302, 2018).
childhood epilepsy syndromes (1 paper, 2022). "Although dominant SCN1B variants are known to be associated with childhood epilepsy syndromes, this study confirms that recessive variants must also be considered in children with Dravet-like phenotypes." (PMID 36291443, 2022).
developmental disability (1 paper, 2022). Disorders in which there is a delay in development based on that expected for a given age level or stage of development. "If found to be safe and efficacious in SCN1B-associated DEE, fenfluramine could be used in early infancy to reduce incidence of developmental disability, status epilepticus and prolonged hospitalizations." (PMID 36291443, 2022).
epilepsy syndrome (1 paper, 2020). A syndrome that has a characteristic cluster of clinical features and/or lectroencephalographic (EEG) findings that reflect underlying epileptic activity. "Mutations in CACNA1E, SCN1B, and SCN9A were previously associated with various epilepsy syndromes." (PMID 32466254, 2020).
glioma (1 paper, 2022). A benign or malignant brain and spinal cord tumor that arises from glial cells (astrocytes, oligodendrocytes, ependymal cells). "Among the 10 candidates, high mRNA expression of CCL8, FCGR2B, and TUBA4A and low mRNA expression of GABRD, PRAME, and SYN1 were significantly correlated with worse prognosis, while the mRNA expression of CCL18, SCN1B, SNCB, and VSNL1 showed no connection to the overall survival of glioma patients." (PMID 36685974, 2022).
laryngeal carcinoma (1 paper, 2022). Carcinoma that arises from the laryngeal epithelium. "The SCN1B transcription level increased in laryngeal cancer tissues, whereas FDE4B transcription levels decreased." (PMID 36579330, 2022).
Liddle syndrome (1 paper, 2023). A rare genetic form of low-renin hypertension characterized by hypertension associated with decreased plasma levels of potassium and aldosterone. "The genetic test showed that the base duplication in the coding region of SCN1B gene caused a frameshift mutation:c.1789dupC (p.Arg597fs), Liddle syndrome was diagnosed." (PMID 38013303, 2023). "Genetic testing showed a frameshift mutation of c.1789dupC (p.Arg597fs) caused by base duplication in the coding region of the SCN1B gene, which was consistent with Liddle syndrome." (PMID 38013303, 2023). "After obtaining the patient’s informed consent, genetic testing was performed, and the result showed that the base duplication in the coding region of the SCN1B gene caused a frameshift mutation: c.1789dupC (p.Arg597fs), which was consistent with the diagnosis of Liddle syndrome." (PMID 38013303, 2023).
Myocardial fibrosis (1 paper, 2025). "Together, these findings point to a potential mechanistic link between SCN1B dysfunction, myocardial fibrosis, and conduction abnormalities, warranting further investigation in both clinical and experimental settings." (PMID 40763036, 2025).
Myoclonus (1 paper, 2022). Very brief, involuntary random muscular contractions occurring at rest, in response to sensory stimuli, or accompanying voluntary movements. "We report this unique case of a patient with an SCN1B-related early myoclonic encephalopathy, presenting with debilitating cortical and subcortical myoclonus and prolonged status epilepticus with severe psychomotor regression." (PMID 36291443, 2022).
otitis media (1 paper, 2011). Inflammation of the anatomical structures of the middle ear, which is most often caused by an infectious process. "Interestingly, in rats whose ears were inoculated with Streptococcus pneumoniae, one of the most common pathogens in otitis media, scn1b, muc2 and muc5 were among the genes upregulated, although polymorphisms of SCN1B do not appear to have been investigated in COME/ROM previously." (PMID 21857919, 2011).
polymorphic ventricular tachycardia (1 paper, 2021). A ventricular tachycardia that is irregular in rate and rhythm. "SCN1B deletion in mice hearts demonstrated increased peak INa, delayed after-depolarizations, and polymorphic ventricular tachycardia." (PMID 34206182, 2021).
prostate tumor (1 paper, 2018). "In mouse model bearing implanted prostate tumor, SCN1B expression is associated with enhanced growth rate and size, as well as decreases in survival rates." (PMID 29723302, 2018).
sarcopenia (1 paper, 2024). Progressive decline in muscle mass due to aging which results in decreased functional capacity of muscles. "Six biomarkers—BTG2, FOXO3, AQP9, GPC3, CYCS, and SCN1B—were identified alongside a diagnostic model that offers a novel approach for early diagnosis of sarcopenia." (PMID 39777262, 2024). "The highlight of our study is the identification of six potential diagnostic markers for sarcopenia: BTG2, FOXO3, AQP9, SCN1B, CYCS, and GPC3." (PMID 39777262, 2024).
Seizure (1 paper, 2025). A seizure is an intermittent abnormality of nervous system physiology characterized by a transient occurrence of signs and/or symptoms due to abnormal excessive or synchronous neuronal activity in the brain. "Additionally, another pair shared an SCN1B c.363C > G, p.Cys121Trp variant as part of a family with Genetic Epilepsy with Febrile Seizures Plus (GEFS+), which accounted for febrile seizures in both twins." (PMID 40577228, 2025).
status epilepticus (1 paper, 2022). Status epilepticus is defined as a continuous seizure lasting more than 30 min, or two or more seizures without full recovery of consciousness between any of them. "When started in a 28-month-old patient with homozygous SCN1B-associated early infantile DEE, fenfluramine led to a cessation of fever-induced status epilepticus and a reduction in seizure frequency and severity." (PMID 36291443, 2022).
cancer (9 papers, 2014 to 2024). A tumor composed of atypical neoplastic, often pleomorphic cells that invade other tissues. "The present work suggests that transcriptional regulation via the cleaved β1-ICD may play a role in these cellular changes, and that the presence of SCN1B variants may affect cancer outcomes." (PMID 33411695, 2021). "Nevertheless, we identified SCN1B as being the SCNxB gene the most highly expressed in cancer cells." (PMID 27917859, 2016). "While reduced expression of either SCN1B/β1 or SCN2B/β2 decreased cancer cell invasiveness through Matrigel-coated invasion chambers by 42.8±6.6% (n=8) and 51.7±0.3% (n=8) (mean±s.e.m." (PMID 27917859, 2016). "In a recent study, it was nicely demonstrated that SCN1B mRNA and β1 proteins were up-regulated in breast cancer biopsies, compared with non-cancer breast samples." (PMID 26283962, 2015). "Similarly, both CACNG4 and SCN1B are upregulated in cancer tissue and their gene products have been assigned a role in cancer progression." (PMID 32764426, 2020). "The most studied isoform in cancer is SCN1B/β1, and results published so far could appear contradictory." (PMID 27917859, 2016). "The most studied NaVβ protein in cancer is β1, which results from the expression of the SCN1B gene." (PMID 26283962, 2015). "No studies to date have investigated the potential connections between these gene-cancer pairs, therefore, SCN3A-LGG, SCN3B-LGG, SCN4A-KIRC, and SCN1B-PAAD would be potential clinically significant research topics for future study." (PMID 39060933, 2024). "Among these gene-cancer pairs, SCN3A-LGG, SCN3B-LGG, SCN4A-KIRC, SCN1B-UVM, and SCN1B-PAAD have a relatively high gene expression level, and have a relatively large case number except for UVM (n = 79)." (PMID 39060933, 2024). "Importantly, SCN1B and SCN4B genes appeared to be the two most highly expressed SCNxB genes in non-cancer tissues." (PMID 27917859, 2016). "Expressions of SCN1B, SCN2B and SCN3B were lower in cancer compared with non-cancer tissues." (PMID 27917859, 2016).
tumor (7 papers, 2010 to 2023). "On the β2 adrenoreceptor(ADRB2) and sodium voltage-gated channel gene (SCN1B), which mediatesignaling of neurotransmitters through Gs proteins, are positivelycorrelated with HLA-I in the same tumor types." (PMID 37857377, 2023). "Based on the cell line data, we focused on the relationship between SCN8A and SCN1B tumor expression and overall survival from EOC after optimal cytoreductive surgery followed by platinum-based chemotherapy." (PMID 34771603, 2021). "The contrasting prognostic significance of SCN8A and SCN1B tumor expression raised the possibility that VGSC blockade could be either helpful or harmful EOC." (PMID 34771603, 2021). "Our observed 3.70 fold down-regulation of SCN1B in the poor-responders indicates that the tumor environment may become more pro-migratory due to reduced expression of this factor." (PMID 20860831, 2010). "Among patient tumor samples, lower SCN8A expression was associated with improved overall survival (OS) (median 111 vs. 52 months; HR 2.04 95% CI: 1.21–3.44; p = 0.007), while lower SCN1B expression was associated with poorer OS (median 45 vs. 56 months; HR 0.69 95% CI 0.54–0.87; p = 0.002)." (PMID 34771603, 2021). "In addition, in tumour specimens, the positive relationship between SCN1B mRNA and ER status was not reflected at the protein level." (PMID 24729314, 2014).
cardiac disease (4 papers, 2021 to 2025). "In addition, the absence of β1 RIP and downstream signaling, as modeled by Scn1b-null mice, may contribute to cardiac disease mechanisms in patients with SCN1B LOF variants." (PMID 33411695, 2021).
neurological diseases (3 papers, 2018 to 2023). "Thus, it is not surprising that variants in SCN1B are linked to devastating cardiac and neurological diseases with a high risk of sudden death." (PMID 29740331, 2018).
cardiovascular disease (2 papers, 2021 to 2022). "Loss-of-function (LOF) variants in SCN1B, encoding the voltage-gated sodium channel β1/β1B subunits, are linked to neurological and cardiovascular diseases." (PMID 35603785, 2022). "In the human heart, we found that SCN1B transcript expression was 3 times higher in the atria than ventricles, differences that could, in combination with inherited or acquired cardiovascular disease, dramatically affect patient response to class Ib antiarrhythmic therapies." (PMID 34156986, 2021).
genetic disorders (2 papers, 2015 to 2017). "A growing list of SCN1B mutations linked to inherited diseases reveals the important roles that the β1-subunit plays in the NaCh-function." (PMID 26042039, 2015). "WES enabled timely diagnosing of genetic diseases, validation of causality of specific genetic disorders of PTPN23, KCTD3, SCN3A, PPOX, FRMPD4, and SCN1B, and setting dual diagnoses by detecting two causative variants in distinct genes in the same patient." (PMID 27848944, 2017).
SCN1B also shares sentences with these, for which no sentence is quoted: Arrhythmia (4 papers); channelopathies (3); infantile epileptic encephalopathy (3); autism spectrum disorder (2); Brugada syndrome 5 (2); cardiac conduction disease (2); cardiomyopathies (2); Doose syndrome (2); focal epilepsy (2); hearing loss (2); Intellectual disability (2); long QT syndrome (2); Onset (2); schizophrenia (2); alcohol dependence (1); Alzheimer disease (1); atrial fibrillation, familial, 13 (1); bipolar disorder (1); cerebellar ataxia (1); diabetes (1); dyspraxia (1); gynecological cancers (1); infection (1); ischemia (1); ischemic cardiomyopathies (1); long QT syndrome type 3 (1); neurodevelopmental disorder (1); Parkinson disease (1); prostate carcinoma (1); ventricular fibrillation (1).